RWDD1 (RWD domain containing 1)
Description:
Protects DRG2 from proteolytic degradation (By similarity). May function as a coactivator of the AR/androgen receptor transcription factor during development.
Synonyms: DFRP2; CGI-24; PTD013
Tractability: PROTAC: ubiquitination databases record sites on it; its protein half-life has been measured.
Gene: Protein-coding gene on chromosome 6 (116,571,409 to 116,597,675, forward strand). Ensembl gene ENSG00000111832.
Subcellular location: Cytoplasm, cytosol
Pathways (Reactome):
Metabolism of proteins: Protein hydroxylation
Gene Ontology:
Molecular function: protein binding; transcription coactivator activity
Biological process: androgen receptor signaling pathway; cytoplasmic translation; positive regulation of DNA-templated transcription
Cellular component: cytosol; cytoplasm
Genetic constraint (gnomAD): Loss-of-function variants: 3 observed, 11.88 expected, observed/expected ratio (o/e) 0.25, 90% interval 0.11 to 0.65. The upper end of that interval is the gene's LOEUF score, 0.65, which puts it in group 2 of 6, group 1 being the genes least tolerant of losing a copy. Missense variants: 92 observed, 119.18 expected, observed/expected ratio (o/e) 0.77, 90% interval 0.65 to 0.92. Synonymous variants: 43 observed, 42.71 expected, observed/expected ratio (o/e) 1.01, 90% interval 0.79 to 1.3.
Homologues: Orthologues: chimpanzee RWDD1 (100% identical), macaque RWDD1 (100% identical), dog RWDD1 (99% identical), rat Rwdd1 (97% identical), mouse Rwdd1 (96% identical), guinea pig RWDD1 (95% identical), tropical clawed frog rwdd1 (80% identical), zebrafish rwdd1 (79% identical), Drosophila melanogaster CG5515 (44% identical), Caenorhabditis elegans T26E3.4 (37% identical).
Diseases named in the same sentence as RWDD1 in open-access papers:
RWDD1 is named in the same sentence as 4 diseases in open-access papers, as found by Europe PMC text mining. Sharing a sentence is not in itself a finding about the gene and the disease. The quoted sentences say what the papers report.
colon cancer (1 paper, 2014). "Building from our approach, we identified four new putative cancer genes (RWDD1, NCF1, PLEK, and VAV3), whose expression profiles were found to be associated with poor survival rates in melanoma, lung, or colon cancer patients." (PMID 25360158, 2014). "To demonstrate the potential value of our approach, we identified four putative cancer genes (RWDD1, NCF1, PLEK, and VAV3), whose expression was associated with poor survival rates in melanoma, lung, or colon cancer patients." (PMID 25360158, 2014).
colorectal cancer (1 paper, 2014). A primary or metastatic malignant neoplasm that affects the colon or rectum. "Using a statistical framework, we identified four putative cancer genes (RWDD1, NCF1, PLEK, and VAV3), whose expression profiles were associated with overall poor survival rates in melanoma, lung, or colorectal cancer patients." (PMID 25360158, 2014). "We identified four putative cancer genes (RWDD1, NCF1, PLEK, and VAV3), whose gene expression profiles were associated with overall poor survival rates in melanoma, lung, or colorectal cancer patients." (PMID 25360158, 2014).
RWDD1 also shares sentences with these, for which no sentence is quoted: cancer (1 paper); melanoma (1).